ARL4A (ARF like GTPase 4A)
Description:
Small GTP-binding protein which cycles between an inactive GDP-bound and an active GTP-bound form, and the rate of cycling is regulated by guanine nucleotide exchange factors (GEF) and GTPase-activating proteins (GAP). GTP-binding protein that does not act as an allosteric activator of the cholera toxin catalytic subunit. Recruits CYTH1, CYTH2, CYTH3 and CYTH4 to the plasma membrane in GDP-bound form.
Synonyms: ARL4
Tractability: Antibody: its Gene Ontology location is reachable by antibodies, with high confidence; UniProt places it where antibodies can reach, with medium confidence. PROTAC: ubiquitination databases record sites on it.
Gene: Protein-coding gene on chromosome 7 (12,686,602 to 12,690,958, forward strand). Ensembl gene ENSG00000122644.
Subcellular location: Cell membrane; Cytoplasm; Nucleus, nucleolus
Subcellular location (Human Protein Atlas): Cytosol; Nucleoplasm
Gene Ontology:
Molecular function: GTP binding; protein binding; GTPase activity
Biological process: intracellular protein transport
Cellular component: cytosol; nucleolus; nucleus; plasma membrane; cytoplasm
Genetic constraint (gnomAD): Loss-of-function variants: 5 observed, 13.66 expected, observed/expected ratio (o/e) 0.37, 90% interval 0.19 to 0.77. The upper end of that interval is the gene's LOEUF score, 0.77, which puts it in group 3 of 6, group 1 being the genes least tolerant of losing a copy. Missense variants: 147 observed, 228.49 expected, observed/expected ratio (o/e) 0.64, 90% interval 0.56 to 0.74. Synonymous variants: 77 observed, 83.72 expected, observed/expected ratio (o/e) 0.92, 90% interval 0.76 to 1.11.
Homologues: Orthologues: chimpanzee ARL4A (100% identical), dog ARL4A (99% identical), macaque ARL4A (99% identical), mouse Arl4a (99% identical), pig ARL4A (99% identical), rabbit ARL4A (99% identical), rat Arl4a (99% identical), guinea pig ARL4A (98% identical), tropical clawed frog arl4a (89% identical), zebrafish arl4aa (79% identical). Paralogues in human: ARL4C (68% identical), ARL4D (60% identical), ARF3 (42% identical), ARF1 (42% identical), ARF5 (42% identical), ARF4 (41% identical), ARF6 (40% identical), TRIM23 (38% identical), ARL1 (36% identical), ARL5B (36% identical), ARL11 (35% identical), ARL3 (34% identical), and 18 more.
Diseases named in the same sentence as ARL4A in open-access papers:
ARL4A is named in the same sentence as 7 diseases in open-access papers, as found by Europe PMC text mining. Sharing a sentence is not in itself a finding about the gene and the disease. The quoted sentences say what the papers report.
cervical cancer (1 paper, 2023). A primary or metastatic malignant neoplasm involving the cervix. "We found that the expression levels of Arl4A and EGFR in two tested epithelial cervical carcinoma cell lines, HeLa and C33-A, were significantly different." (PMID 38030597, 2023).
cancer (6 papers, 2021 to 2025). A tumor composed of atypical neoplastic, often pleomorphic cells that invade other tissues. "We infer that the enhanced EGFR degradation following Arl4A-depletion is unrelated to the EGFR degradation resistance machinery elicited by these cancer-associated EGFR mutations." (PMID 38030597, 2023). "Thus, we conclude that Arl4A also participates in endolysosomal delivery and degradation of cancer-associated EGFR mutants." (PMID 38030597, 2023). "In Cluster 7, no major characteristics were observed for DCDQ, SCQ, or RBS-R scores, whereas ARL4A and ETV were associated with cancer." (PMID 40440618, 2025).
ARL4A also shares sentences with these, for which no sentence is quoted: Hernia (1 paper); Huntington disease (1); lung carcinoma (1); lupus (1); lymphoma (1).